AR (androgen receptor)
Diseases named in the same sentence as AR in open-access papers (continued):
Sharing a sentence is not in itself a finding about the gene and the disease.
tumor (continued). "However, even though IL-6 seems to be associated with tumor progression, its relationship with the AR is convoluted and IL-6/STAT3 can have both pro and anti-proliferative effects on tumor cells as that depends on AR status of PCa cells well as activity/crosstalk from other pathways." (PMID 24722453, 2014). "These lines express AR and PSA, and respond to castration with tumor regression and prolongation in progression-free survival (PFS), but ultimately progress to castration-resistant growth (p<0.0001 for both)." (PMID 25356728, 2014). "CN analysis showed that the PIK3CA locus was amplified (1.544, 1.436, and 1.316, log2) in AR+/PIK3CA mutant tumors, including one tumor (TCGA-C8-A12L) with a focal amplification of only 12 genes." (PMID 25103565, 2014). "The exclusive requirement of PCa cells for AR activity is illuminated at clinic, wherein therapeutic suppression of AR signaling, typically achieved through ligand depletion and direct AR antagonists, results in PSA decline and objective tumor regressions." (PMID 25520915, 2014). "Of note, we demonstrated that LAR cells are in part dependent on AR signaling as siRNA-mediated AR knockdown or pharmacological inhibition of AR by bicalutamide (CDX) greatly decreases cell viability and tumor growth." (PMID 25103565, 2014). "In the present study, we investigated the dependency of AR on FOXA1 expression in tissue paraffin sections, in multiple cellular contexts, and on tumor-bearing nude mice." (PMID 24512546, 2014). "Any combination of these AR activating changes in CRPC tumors makes them hypersensitive to androgen and tumor growth resumes as in androgen dependent conditions." (PMID 24722453, 2014). "Tumor tissues were then embedded in paraffin, stained with hematoxylin and eosin (H&E), and immunohistochemically stained with antibodies against FOXA1, AR, Notch1, Hes1, Ki67, or PCNA." (PMID 24512546, 2014). "To determine the expression of CAMK2N1, AR, pAKTser473, PSA, Bax, Bcl-2, p21, and Ki67 in tumor tissues, we conducted qRT-PCR and IHC staining in tumors." (PMID 25296973, 2014). "Consistent with the undifferentiated tumor histology, all HPCa/Hs5 tumors lack PSA and only express very low levels of AR." (PMID 23451107, 2013). "miR-205 has been shown to be epigenetically repressed tumor suppressor in PCa that exerts its tumor-suppressive functions in the human prostate through down-regulation of multiple targets such as BCL2, protein kinase C epsilon and androgen receptor (AR)." (PMID 24167554, 2013). "Recent studies have shown that the AR and PI3K/AKT signaling pathways inversely regulate each other in Pten null tumor cells." (PMID 23308230, 2013). "Thus, hormonal therapy may interfere only with the bulk population of AR-expressing cells, while the AR-negative, more primitive tumor initiating cells survive hormonal therapy and give rise to progeny that have developed a mechanism to escape hormonal therapy." (PMID 23819124, 2013). "We first compared AR copy number, determined by FISH, with the AR transcript abundance, determined by cDNA microarray, from the same tumor sample." (PMID 24098661, 2013). "However as this does not completely eliminate circulating androgens, sufficient concentrations of dihydrotestosterone may accumulate in tumour cells to maintain AR signalling, especially in the context of up-regulated receptor levels or increased sensitivity of the AR for activation." (PMID 23945560, 2013). "A panel of phosphospecific antibodies were employed to study AR phosphorylation in 84 matched HNPC and CRPC tumours." (PMID 23945560, 2013). "IL-6, a multi-functional cytokine, is the main activator of STAT3 signaling and the inducer for androgen receptor (AR) expression, STAT3 activation has been reported to mediate the radioresistance of tumor, and be up regulated by IL-6." (PMID 23806095, 2013).
tumor (continued). "In vivo, LNCaP/AR cells overexpressing either AR WT or F876L were grafted subcutaneously into castrate SCID mice and time to tumor emergence/progression was determined in the presence or absence of drug." (PMID 23580326, 2013). "Whilst all the spindle cells within the tumour expressed CD34, AR, ER, BCL2, and CD10, only those within the myofibroblastoma expressed desmin and only those within the lipomatous areas expressed S100." (PMID 24459597, 2013). "Ex vivo studies of castration resistance prostate tumors displayed a significant anti-tumor response to both veliparib and olaparib, two well-known PARP inhibitors, that correlates with reduced AR activity." (PMID 24350055, 2013). "Studies have shown that AR is expressed in the vast majority of CRPC tumors, is transcriptionally active, and is required for tumor cell growth." (PMID 26877888, 2013). "FOXA1 and AR immunostainings were positive in 90% and 58% of MA tumors, respectively, and 57% were positive for GCDFP15 with 5% to 90% stained tumor cells (median 50%)." (PMID 23663520, 2013). "It was reported that castration-resistant bone marrow metastasis tumors and circulating tumor cells from CRPC patients express AR-regulated genes, indicating persistent activation of the AR signaling axis despite castration." (PMID 23896594, 2013). "The main tumour spindle-shaped cells as well as those entrapped within the fat lobules were positive for CD34, BCL2, ER, AR, and CD10 (weak)." (PMID 24459597, 2013). "As expected, the HPCa57 patient tumor exhibited typical GS7 histology with crowded tumor glands, in which most cells stained positive for prostate luminal epithelial cell markers PSA, nuclear AR, and cytokeratin 8 (CK8)." (PMID 23451107, 2013). "In this study, we tested our hypothesis that suppressing AR function via siRNA in PCa might simultaneously trigger undesirable inflammatory signals that would prompt macrophage infiltration and thereafter could provide tumour-supporting signals to stimulate progression of PCa." (PMID 23982944, 2013). "AR and PSA mRNA levels in LNCaP tumor xenografts from intact Non obese diabetic/Severe Combined ImmunoDefficiency (NOD/SCID) mice were comparable to the R1881 stimulated 3D cultures but not the 2D cultures." (PMID 22957009, 2012). "Previous studies have reported that tumor specimens from women of African-American heritage are significantly more likely to lack expression of the hormone receptors ESR1, PGR, and AR, compared to other ethnicities." (PMID 22616718, 2012). "Levels of PSA, a classic target gene of AR, secreted by the AR-positive xenografts were measured in the mouse sera using a human-specific PSA ELISA kit and were normalized to tumor weights." (PMID 22479342, 2012). "Tumor-bearing mice were treated by Luteinizing-Hormone Releasing Hormone (LHRH) antagonist alone, continuous or intermittent regimen, or combined with androgen receptor (AR) antagonists (bicalutamide or flutamide)." (PMID 22879924, 2012). "Tumour specimens from these patients were graded histopathologically, and immunnohistochemistry for Ki-67, CD31, androgen receptor (AR), Her-2/neu, Bcl-2, and PTEN were performed." (PMID 23077456, 2012). "This pattern suggests inverse relation between SATB1 and HIF-1α co-expression and the co-expression of AR, ER, and BCL2 in the subgroup of HR-positive tumours." (PMID 22424533, 2012). "The mechanisms by which these more aggressive tumors retain AR activity and AR-mediated gene expression are still unclear, although it has been hypothesized that the development of intratumoral steroidogenesis may contribute to castration-resistant tumor growth." (PMID 22614157, 2012).
tumor (continued). "We conclude that androgen-dependent and androgen-independent AR signaling can coexist in CRPC, with their relative importance dependent on AR activity and androgen levels in tumor microenvironment." (PMID 23019221, 2012). "Univariate analysis showed that the significant prognostic factors included age, tumor size, tumor grade, Lauren type, T classification, N classification, radical resection, TNM stage, ERα expression, and AR expression." (PMID 23199240, 2012). "The tumor tissues were removed and analyzed by immunohistochemistry using anti-phosphor-AMPKα, phosphor-ACC and AR antibodies." (PMID 23056607, 2012). "In cultured mouse granulosa cells and a steroidogenic human ovarian granulosa-like tumor cell line, KGN, mRNA and protein expression levels of AR were increased by overexpressing Nur77 but decreased by knocking down endogenous Nur77." (PMID 22761936, 2012). "With high levels of endogenous wild type AR and TMPRSS2-ERG fusions as well as expression of many prostate epithelial markers, these cells serve as a useful model for CRPC tumor progression and metastasis." (PMID 22849360, 2012). "To assess if Nur77 also regulates the transcription of the human AR gene, we treated KGN cells, a human granulosa-like tumor cell line, with Ad-Flag-Nur77 at the indicated MOI for 48 h." (PMID 22761936, 2012). "Since PCa is initially dependent upon AR signaling, hormone therapy (also referred to as androgen deprivation therapy or ADT) is often used to target and reduce AR-mediated growth of the tumor." (PMID 22746994, 2012). "Given their reduced levels of AR expression, the PTEN deleted tumor cells are expected to be less responsive to androgen ablation treatment." (PMID 23171135, 2012). "Decoy AR1-558 inhibits full-length AR and blocks both androgen-dependent and CRPC tumor growth, most likely by a mechanism of mopping up essential proteins required for transcriptional activity." (PMID 22111003, 2011). "In line with this we correlated AR expression with the expression of ILK, p-Akt, E-cadherin, β-catenin in our sample as well as with tumor grade and TNM stage." (PMID 22191056, 2011). "Because the transcriptional activity of AR and HIF-1α was attenuated by panobinostat/everolimus combination in vitro, we asked if these events were critical for the superior anti-tumor activity of panobinostat/combination therapy in vivo." (PMID 22087262, 2011). "In this report we used the AR-positive LNCaP sublines C4-2 and LNCaP-SSR which are both known to grow and survive under androgen-deprived conditions as an in vitro tumor model for CRPC." (PMID 21980429, 2011). "Interestingly, the same authors demonstrated GLIexpression in localised prostate cancer; this may be unexpected as primary tumoursare considered to display a predominantly luminal phenotype (i.e.p63−/AR+) but this probably reflects lower GLIactivity compared to more aggressive tumours." (PMID 21633508, 2011). "Tumor cells showed positive nuclear immunostaining for human AR and cytoplasmic staining for human PSA, confirming the tumor origin as LNCaP C4-2 cells." (PMID 20946682, 2010). "Up-regulation of VAV3 and TWIST1 oncogenes and repression of the DKK3 tumor-suppressor was observed in PC346DCC, suggesting a potential AR bypass mechanism." (PMID 20976069, 2010). "In contrast, androgens and the androgen receptor (AR), which is expressed and functional in both LNCaP and CWR-22RH cells, have been reported to suppress TSP1 expression in tumor cells." (PMID 20470445, 2010). "Ebp1 can also repress the transcription of androgen receptor (AR) and Cyclin D1, through physically binding to the AR or by interacting with the histone deacetylase HDAC2 and the tumor suppressor Retinoblastoma (Rb)." (PMID 19025630, 2008).
tumor (continued). "The functionality of AR in these resistant cells is well established, but this does not foretell if AR silencing is sufficient to inhibit proliferation and trigger apoptosis, as other molecular events accumulating along tumor progression could help cells bypassing AR signaling." (PMID 17925854, 2007). "Western blotting was used to evaluate changes in expression of β-tubulin, HER2, p-ERK, p-AKT, p27, BCL2, AR, HSP90 and HSP70 induced by treatment with docetaxel alone or the trastuzumab plus docetaxel combination in HID28 tumours, a very high responder." (PMID 17211467, 2007). "In the present study, we investigated AR amplification, AR protein expression and PSA expression in paired hormone-sensitive and hormone-resistant tumours from the same patient with documented initial responses to androgen deprivation therapy." (PMID 12888829, 2003). "The absence of AR expression remarkably attenuates the effect of ZMIZ2 in promoting tumor cell proliferation." (PMID 41431399, 2026). "Pharmacologic disruption of these coactivators abrogates noncanonical AR activity and suppresses tumor growth, highlighting a tractable vulnerability." (PMID 41602415, 2026). "IHC revealed a positivity of the tumor cells for BerEp4, AE1/AE3, GATA‐3, Androgen Receptor (AR, 10%), CAM5.2, Estrogen Receptor (ER, 70%), Ki67 with a score of 10% and Progesterone Receptor (PR, 10%), negativity for TTF‐1, GCDFP‐15, HER‐2, HBME‐1, and Calretinin." (PMID 41239938, 2026). "Our analysis revealed clear negative correlations of pan-cancer AR activity with tumor immune infiltrates in both sexes." (PMID 41486951, 2026). "Certain AR-independent signaling pathways, including the PI3K-AKT 9, NF-κB 10, Wnt 11, and glucocorticoid pathways 12, are also affected by Enz and play an equally important role in exerting anti-tumor effects and extending patient survival." (PMID 40303302, 2025). "Inhibiting KIFC1 using the small molecule inhibitor CW069 significantly reduced tumor volume in mice bearing AR-TNBC xenografts, but not in those with triple-negative breast tumors." (PMID 40448099, 2025). "Second-generation AR inhibitors, PARP inhibitors, and PSMA-targeted agents significantly improve survival, while immunotherapies like checkpoint inhibitors and vaccines rekindle anti-tumor immunity." (PMID 41200193, 2025). "Consequently, elucidating the relationship between the AR and immunity in different cell types within BC, as well as investigating the role of the AR in bladder development, may enhance our ability to manage tumor occurrence, progression, and treatment through immune modulation." (PMID 40007149, 2025). "Truncated AR isoforms lead to the constitutive activation of AR on tumor cells, making them independent of androgen proliferative stimuli." (PMID 40002869, 2025). "Because luminal tumor cells should be highly represented in these samples, we first performed the analysis using Lum_Mut signatures (derived independently from GEMM clusters 11, 3 and 4), or using either of two widely used human AR pathway signatures." (PMID 40858905, 2025). "These pathways make the tumor cells more resistant to programmed cell death (apoptosis), allowing them to survive longer and become harder to eliminate, even without AR involvement." (PMID 41235005, 2025). "Additionally, the anti-tumor activity of ATR-I was diminished after KIF15 overexpression in AR+ and AR− CRPC cells, indicating that KIF15 expedited CRPC progression in both an AR-dependent- and independent manners, such as the EGFR signaling pathway." (PMID 40087774, 2025). "A directly AR-repressed gene is the lncRNA MIR503HG, which exhibits increased expression in metastatic PCa further supporting the notion that SAL induces a suppressive tumor pathway." (PMID 41264145, 2025).
tumor (continued). "Notably, enzalutamide induced degradation of the phosphorylated AR-SPOP complex, restoring sunitinib sensitivity in vivo and promoting tumor regression in the 786-O model." (PMID 40521202, 2025). "Similarly, miR-200a-3p acts as a tumor suppressor by downregulating STAT4 and modulating PD-L1 expression through its interaction with AR-induced circRNAs." (PMID 40806474, 2025). "Additionally, a study identified OCT4 as a key transcription factor in CRPC and NEPC, collaborating with FOXA1, AR, and NRF1 to drive the tumor progression." (PMID 40722714, 2025). "Therapeutically, restoring miR-137 expression or inhibiting AR and SKI activity could disrupt this FFL and suppress tumor progression." (PMID 40862714, 2025). "Additionally, pathways such as androgen receptor signaling and RAS/MAPK contribute to tumor progression and present potential therapeutic targets." (PMID 39968094, 2025). "However, it has a therapeutic value in women, for instance in treating AR+ BC and AR+ TNBC since it can block the use of androgens by the tumor cells." (PMID 40002228, 2025). "Upon AR pathway inhibition, there may be a consequent up-regulation of PSMA; however, if the tumor undergoes neuroendocrine differentiation (NED), driven by factors like N-Myc and EZH2, epigenetic silencing of FOLH1 results in PSMA-low or -negative subclones." (PMID 40806607, 2025). "Additionally, the tumor cells expressed human epidermal growth factor receptor 2 (HER2) and were positive for the androgen receptor (AR)." (PMID 40959352, 2025). "Previous studies have also identified a variety of molecules or pathways that not only involve tumor progression and metastasis, including epithelial-to-mesenchymal transition (EMT) and angiogenesis, but also are modulated via AR signals in urothelial cancer cells." (PMID 40486871, 2025). "Additionally, the TME reflects an intricate network of signals from AR pathways to the PI3K/AKT pathway, which collectively shapes tumor-immune dynamics and underscores the potential for integrated therapeutic strategies." (PMID 40427518, 2025). "Tumor organoids also established syngeneic allografts in C57BL/6 host mice while retaining their adenocarcinoma histology and expression of transgenic FOXA1, AR, and CK8 luminal markers." (PMID 40570057, 2025). "Similarly, stromal AR correlated with PSA score and inversely with tumor Ki67, suggesting that PSA-high/MetA-enriched metastases have a more androgen-responsive stroma compared to Ki67-high/MetB-enriched metastases." (PMID 40841830, 2025). "We had therefore most likely focused on patients suffering from small tumor volumes, who had not undergone systemic treatment such as chemotherapy or androgen receptor pathway inhibitors." (PMID 39792324, 2025). "Despite assertions that it exerts a tumor-suppressive role in PCa, NKX3.1 has become an excellent and widely used IHC biomarker for metastasis of prostatic origin; it is even more reliable than traditional AR or prostate-specific antigen (PSA) staining." (PMID 39858088, 2025). "The lack of functional validation further limits our ability to confirm whether AR and TAN actively influence tumor differentiation, invasiveness, and vascular involvement." (PMID 40734715, 2025). "Taken together, these reports indicate an important role for classical RSGs in promoting tumor metastasis through both genomic and non-genomic mechanisms mediated by nuclear and membrane-localized AR." (PMID 41301045, 2025). "Tumor cells with high expression of AR may die during ADT, whereas those with low expression of AR may survive and proliferate." (PMID 39711287, 2025).